CD68 (CD68 molecule)
Diseases named in the same sentence as CD68 in open-access papers (continued):
Sharing a sentence is not in itself a finding about the gene and the disease.
tumor (continued). "CD68+ macrophage infiltration surrounding tumor blood vessels was often observed." (PMID 36831707, 2023). "Among the proteins exclusively detected in tumor, CD68 as a macrophage marker stands out." (PMID 36508875, 2023). "In addition, in the range of less than 20 um to 80 um, S15+ tumor cells were surrounded by more CD68+ TAMs, and spatially closer to CD68+ TAMs than S15− tumor cells." (PMID 37674198, 2023). "Other pre‐treatment biomarkers, including CD3+, CD8+, CD3 + CD4+, CD20+, CD68+ tumor‐associated macrophages (TAM), NK cells, and TLS, were not different between the TRG 1–3 and TRG 4–5 groups." (PMID 36341590, 2023). "Furthermore, analysis from the TISIDB dataset showed that ACT1 level in tumor tissues negatively correlates with the number of CD68+ macrophages infiltration in CRC tumor tissues." (PMID 36978108, 2023). "We found that the mean tumor area covered by CD68-immunopositive macrophages was 4.94%." (PMID 37237550, 2023). "A meta-analysis found that a high density of CD68 macrophages in the tumor microenvironment was associated with a better prognosis and a lack of tumor metastasis in CRC patients." (PMID 37525217, 2023). "Our results suggested that the high CD68+ TAMs infiltration in TME was significantly associated with poor OS and DFS, whether identified in the tumor or TS." (PMID 36633963, 2023). "Interestingly, we found similar macrophage subtypes in the CD68+ cells from the original tumor as in the co‐culture assay, except for MC3, the TransMo population that was artificially generated by GM‐CSF stimulation (Fig EV4E–G)." (PMID 37791581, 2023). "Cluster 2 had the highest expression and diversity of M1 and M2 macrophage markers, in particular the general macrophage marker CD68, anti-tumor markers CD169, HLA-DR, STING, and CD38, and pro-tumor markers CD163, CD204, and CD206, and immune checkpoint molecules PD-1 and PD-L1." (PMID 37620318, 2023). "Macrophages can be recruited to areas with damage, such as inflammation or necrosis, but not all macrophages stained by CD68 are tumor-associated macrophages." (PMID 36980192, 2023). "The, CD68 TAMs are positively correlated with tumor size, metastasis, and angiogenesis." (PMID 37941832, 2023). "In particular, a high density of CD68+ TAM was associated with a higher density of micro-vessels and vascular endothelial growth factor A (VEGF-A), markers of vascular neovascularization and tumor remodeling." (PMID 37465638, 2023). "IOPN tumor cells presented an activated PD-1/PD-L1 axis and a surrounding microenvironment characterized by a larger number of B cells than T cells (p < 0.001) and CD68+/CD163+ macrophages, mainly located within the tumor." (PMID 37086293, 2023). "Notably, except for the CD68+ macrophages, which were generally more abundant in the cancer than in the tumor margins, leucocytes were typically more abundant in the tumor margins than in the cancer." (PMID 37190147, 2023). "Likewise, there was no systematic difference in the presence of monocytic cells in TLR7−/− or TLR7wt KPC tumors as evaluated by CD68 staining of representative tumor sections." (PMID 36602302, 2023). "In conclusion, we identified that the number of CD68+ TAMs in TN of KT tissues is an independent risk factor affecting OS in patients with CRC or GC combined with KTs, whereas tumor resection range might be an independent risk factor affecting PFS in patients." (PMID 36910657, 2023). "It is hypothesized that TAMs at the invasive front in CLM exhibit an immunosuppressive role by PD-L1 expression.The tumor periphery also had relatively higher density of CD68+CD163+CD206neg M2 macrophages than the center." (PMID 37637998, 2023). "In addition, we observed a qualitative increase in the CD68+ myeloid population in the organ already after 7 days of the tumour cell injection, which was more pronounced on Day 14 after tumour injection." (PMID 37177862, 2023).
tumor (continued). "The MIF staining results of the tumor immune microenvironment in our study suggest that the baseline infiltration density of PD‐L1/CD68 double‐positive macrophages might be a predictive indicator of the efficacy of LP002 plus chemotherapy." (PMID 36341590, 2023). "To explore whether the immune cell subsets of tumor tissues with high expression of ICOSLGTCs in OSCC patients changed, we determined the ICOSLG, CD4, CD8, CD19, CD68 and Foxp3 level of tumor centers and infiltration fronts in serial sections." (PMID 37842091, 2023). "•Macrophages (CD68+) migrate into the tumor and interact with CD3, CD8 and CD20." (PMID 38219446, 2023). "Dissecting TAMs subsets in this tumor model revealed that BNCT increased CD68+ and F4/80+ TAMs." (PMID 37886177, 2023). "The top 5 proteins exclusively detected in tumor in ≥ 90% of the cases included CD68 (a macrophage marker), Optineurin (OPTN), Nuclear receptor coactivator 5 (NCOA5), RAP1GDS1 (Rap1 GTPase-GDP dissociation stimulator 1) and Stromal cell derived factor 2 like 1 (SDF2L1)." (PMID 36508875, 2023). "CD8+ T cells were positively associated with TAM phagocytic marker CD68 in the infiltrating zone and leading edge (P < 0.001), but not in the tumour core." (PMID 37324244, 2023). "We observed a decrease/loss of association of TSPO expression and CD68 expression with increasing tumor cell content (no tumor: r = 0.686, p < 0.001; some tumor: r = 0.414, p < 0.001; infiltration zone: r = 0.403, p < 0.001; solid tumor: r = 0.027, p = 0.472)." (PMID 37697350, 2023). "Three studies analysed CD68+ in the stroma and intra-tumour location of OSCC." (PMID 37397243, 2023). "Besides, the number of CD68+ macrophages in the stroma of the tumor was much higher in ACT1-low expression tumors than that in ACT1-high expression tumors of CRC patients." (PMID 36978108, 2023). "CD68-positive or CD163-positive macrophages were mainly detected in the tumor stroma." (PMID 37749297, 2023). "Thus, it can be estimated that CD68-positive cells can be supportive of combined immune therapies, as they were positively related to the infiltration of immune cells in many tumor types." (PMID 38201286, 2023). "In GBM, TAMs (both circulating macrophages and resident brain microglia) represent nearly half of the tumor mass, and the presence of CD68, a microglial marker, using a combination of tissue microarrays (TMA) and transcriptomic analyses, has been correlated with the clinical outcome of patients." (PMID 37370866, 2023). "Furthermore, FAT4 expression was associated with markers of tumor-associated macrophages, such as CCL2, CD68, and IL-10." (PMID 37735184, 2023). "In tumor tissues with a high SIGLEC1/CD68 ratio, there was an increase in the infiltration and function of cytotoxic lymphocytes, based on the expression of the T cell receptor CD3 complex subunit (CD3E), natural cytotoxicity receptor (NCR1), and interferon gamma (IFNG)." (PMID 36266311, 2022). "Similarly, the only another significant correlation that was evidenced was between the eight tumor samples bearing a concomitant positive staining for CD68 and CD163 above 5%, the presence of GC and a worse OS and EFS (p = 0.0515 and p = 0.0372, respectively)." (PMID 35326631, 2022). "Thus, the comparison of α-SMA and CD68 expression levels between normal and tumor samples represents the mobilization of these stromal cell populations during the tumorigenic process." (PMID 35711892, 2022). "The cluster of differentiation CD68, overexpressed in TAMs, not only indicates the amoeboid, phagocytic phenotype of those cells but it is also related to a higher-grade tumor, Ki67 positivity, and tumor aggressiveness." (PMID 36589283, 2022). "Additional correlation analyses showed that IL7R expression was significantly associated with markers of cells involved in immunosuppression such as CD68, CD163, MRC1, and IL10 (tumor‐associated macrophages), CD4, FOXP3 (regulator T lymphocytes) and CD274 (PD‐L1)." (PMID 36054746, 2022).
tumor (continued). "Infiltration of macrophages in the microtissues, detected by CD68 and CD163 immunohistochemistry, may be positively associated with a high level of angiogenesis and tumor progression to malignancy." (PMID 35877331, 2022). "The CD8+ and CD68+ immune cell expression in both cancer types was evaluated, and a topographic distribution profile as well as the proportion of both cell populations within the two tumor entities was assessed." (PMID 35463364, 2022). "This was paralleled by a drastic decrease in the number of Cd45+Cd68+F4/80+ tumor associated macrophages (TAM), with a nonsignificant trend toward an increase with rescue cells." (PMID 36221913, 2022). "Furthermore, CD68+ macrophage infiltration affects gene expression within the tumour which impact cell processes like cell death and cell cycle." (PMID 35664673, 2022). "Our data demonstrated that GPX8 was correlated with mRNA expression of immune markers of CD8+ T cells (CD8B), CD4+ T cells (CD4), T cells (CD3D), macrophages (CD68 and ARG1), neutrophils (ITGAM and CCR7), dendritic cells (NRP1), NK cells (B3GAT1), and tumor-associated fibroblasts (FAP)." (PMID 36061208, 2022). "However, nuclear GSDMD was negatively related to CD68+ macrophages in the tumor invasive front and CD8+ lymphocytes in the tumor center." (PMID 35739593, 2022). "To explore the potential role of CA12 expression by monocytes and macrophages in disease progression, we divided HCC patients who had undergone curative resection with follow-up data into 2 groups according to the median value of CD68+ or CD68+ CA12+ cell density in tumor tissues." (PMID 35362480, 2022). "Notably, both the PD-1 expression in the CD68 + TAMs and tumor size were greatly reduced in a B16-F10 tumor mouse model." (PMID 35482149, 2022). "To survey for the presence of infiltrating immune cells in cancer tissue, we measured central immune cell markers (CD8a, CD11c, CD16 and CD68) simultaneously and categorized the present cohort into highly infiltrated (“hot”) tumor and lowly infiltrated (“cold”) tumor samples." (PMID 36139700, 2022). "Inhibiting CD68-dependent signaling could be a promising therapeutic strategy for immunotherapy in many tumor types." (PMID 35550532, 2022). "According to the immunohistochemical results from our clinical samples, both CD163 and CD68 expression was positively correlated with VM enhancement, suggesting that the increased recruitment of TAMs was associated with VM enhancement in RCC tumor tissues." (PMID 35443741, 2022). "Moreover, some tumor cells demonstrated positive staining for CD68, so this marker was excluded from the following analysis." (PMID 35681497, 2022). "In addition to CD86 protein expression and co‐expression of CD68 and CD163 status, statistically remarkable clinicopathological features that were associated with RFS were TNM stage (P =.001) and tumour differentiation (P =.010)." (PMID 34964155, 2022). "This study has also found the CD20 expression to beassociated with CD68 in the tumor stroma." (PMID 36694901, 2022). "In the tumour microenvironment, genes encoding tumour-related macrophage activities, such as the LYZ (lysozyme), TYMP (thymidine phosphorylase), and CD68 (pan-macrophage) genes, may affect the NLR." (PMID 34997351, 2022). "This evaluation confirmed a large presence of CD68+/HO‐1+ macrophages (orange cells), which mainly had two patterns of expression: in the areas surrounding the necrotic tissue or spread in the tumor tissue." (PMID 36054818, 2022). "In addition, our previous study demonstrated that the infiltration of CD68+ cells into the tumor increased during tumor progression and that a high infiltration of such macrophages correlated with shorter survival." (PMID 36428652, 2022). "Then we performed macrophage specific CD68 staining on tumor tissues to further clarify whether the amount of TAMs was changed after radiotherapy." (PMID 35062905, 2022).
tumor (continued). "The reduced expression of CD68, a marker of phagocytic macrophages inside the tumor, correlates with the reduction of the ameboid morphology of TAMs promoted by KCa3.1 channels inhibition, allowing us to also validate the functional properties of TAMs in the TME in response to TRAM-34." (PMID 36589283, 2022). "Jamiyan and colleagues reported that infiltration of CD163+ TAMs, rather than CD68+, in both tumor stroma (TS) and tumor nests (TN) was associated with poor prognosis in patients with triple-negative breast cancer (TNBC)." (PMID 35053472, 2022). "Moreover, in addition to having more immunosuppressive infiltrating immune cells, higher-grade meningiomas appear to express more PD-L1 on tumor cells and tumor-infiltrating CD68+ macrophages." (PMID 35936751, 2022). "Moreover, many previous studies investigating the role M2 macrophages in the tumor microenvironment have characterized those macrophages based on expression of CD68 and CD163." (PMID 35503656, 2022). "Interestingly, CD68/RPS27 double staining indicated that almost all macrophages in tumor tissue were positive for RPS27 compared to a minority in inflammatory tissue." (PMID 36425564, 2022). "Furthermore, some researchers clearly state that a high expression of total CD68 + macrophages in patients with MM leads to poor results that are unrelated to tumor load or disease stage." (PMID 35593325, 2022). "In addition to CD11c, antigen presenting (HLADR and β2M), costimulatory molecules (CD40, ICOS) as well as STING and CD68 were all upregulated in tumor compared to TAS." (PMID 36230846, 2022). "However, CD68+TAMs in the tumor nest (TN) were an independent prognostic marker for shorter OS and DFS in IBC." (PMID 35372038, 2022). "Interestingly, we observed a decrease in the abundance of PD-L1+CD68+ macrophages in the Io+Chemo-treated tumor stroma over that of Chemo alone." (PMID 36275670, 2022). "However, the higher CD8+ and CD68+ infiltration in all tumor regions, namely, the tumor epithelium, the tumor stroma, the entire tumor (epithelium and stroma), and the tumor invasion front was more distinct in cSCC compared to that in BCC." (PMID 35463364, 2022). "Tumour cell positivity was also observed for CD68 and CD3, and the subsequent quantification analysis clearly indicated that both stilbenes can induce a statistically significant decrease of all the immune cell types considered, as compared to vehicle tumour masses." (PMID 35892684, 2022). "Indeed, within serial sections of PDLIM2-positive tumours, there was considerable overlap in the profile of CD68 and PDLIM2 stromal staining, while the expression of CD68 within the tumour was similar in all cores." (PMID 36531051, 2022). "In this model, the number of infiltrating F4/80+, CD11b+ and CD68+ macrophages increased drastically 8 weeks after injection of tumor cells into the peritoneal cavity, and macrophages displayed M2-polarization markers (by the expression of CD163, CD206 and CX3CR1)." (PMID 35682890, 2022). "These intratumoral cells were characterized by CD68 immunostaining, to confirm them as monocyte-derived macrophages which in the liver may be represented by Kupffer cells and tumor-infiltrating macrophages." (PMID 35458213, 2022). "In an American study with 81 PCa patients, TAM density within tumor area positively correlates with Gleason score as confirmed in a Turkish study involving 100 patients in which density of CD68+ TAMs infiltration even correlates with tumor stages, extracapsular extension and perineural invasion." (PMID 36338516, 2022). "We also assessed the tumor-infiltrating macrophages (CD163+CD68+) in tumor samples." (PMID 35836810, 2022). "SIRPα and CD68 were not expressed by cancer cells but rather by tumor-associated macrophages (Μφ, TAMs)." (PMID 35406573, 2022).
tumor (continued). "It is notable that features of immune suppression, characterized by increased proximities of CD8 and CD68 cells to PD-L1–expressing tumor and the increased infiltration of PD-L1+ macrophages and CD8 cells, are observed in patients expressing high levels of gp78." (PMID 35639484, 2022). "The TME with high SPI1 expression level can simultaneously maintain high CD68 + macrophages, implying that SPI1 may be located in M2 macrophages and contributes to tumor-associated macrophage-mediated cancer progression." (PMID 36477668, 2022). "It has recently been shown that upregulated CD68+ fibroblasts are involved in tumor initiation, but the subset of CAFs with low CD68 expression in OSCC is conducive to the recruitment of regulatory T-cells (Treg) in the tumor microenvironment and contributes to a poor prognosis of OSCC patients." (PMID 35406584, 2022). "The level of tumor-infiltrating macrophages (TIM) measured by CD68-positive cells was also studied." (PMID 36289746, 2022). "Immunohistochemically, tumor cells were positive for CD68 and vimentin." (PMID 35220968, 2022). "In addition, we studied the correlation between tumor mutation burden (TMB) and microsatellite instability (MSI) with CD68 levels." (PMID 35550532, 2022). "TBXAS1 is expressed in both CD68 + macrophages and the tumor epithelium." (PMID 36277993, 2022). "CD68 + cells represented the most abundant immune cell present in tumor tissues." (PMID 35659676, 2022). "Second, we could have identified a more restricted population of CD68+CD163+CD206+ M2 TAMs in a tumor microenvironment that is relatively less infiltrated by other CD68+CD163+ TAMs." (PMID 36230752, 2022). "Importantly, out of all PDLIM2-positive tumours, 40% expressed high levels of CD68 compared to less than 10% of the PDLIM2-negative tumours." (PMID 36531051, 2022). "The specific mechanisms of CD68 in tumor growth and metastasis are unclear." (PMID 35550532, 2022). "When it comes to tumor macrophages, we could observe similar results for CD68+ cells compared to those of the CD8+ T-cell group with a significantly more dominant expression in cSCC compared to BCC." (PMID 35463364, 2022). "The observation that certain TIICs, including CD68+ cells, were enriched in the tumour region suggested that the proximity of TIICs to tumour cells might influence their phenotype." (PMID 35982052, 2022). "CD68 plays a critical role in promoting phagocytosis; however, the function of CD68 in tumor immunity and prognosis remains unknown." (PMID 35550532, 2022). "The CD8+ and CD68+ immune cell expression in both cancer types was evaluated by immunohistochemistry and a topographic distribution profile, and the proportion of both cell populations within the two tumor entities was assessed." (PMID 35463364, 2022). "In addition, the expression of SIRPA and macrophage markers (CD68 and CD163) in tumor-associated immune cells (TAIs) was analyzed." (PMID 33799989, 2021). "Based on the known annotation of marker genes from the literature, we grouped cells of nine clusters into four cell types: GNP-like tumor cells (expressing Math1 and Grin2b), microglia (expressing Aif1 and Cd68), T cells (expressing Cd3d and Cd3e), and endothelial cells (expressing Cldn5 and Cdh5)." (PMID 34210306, 2021). "Pearson correlation coefficients were calculated, and the results indicated that BGN presented the strongest correlations with TIIC markers for monocytes (CD86, CD115), tumor-associated macrophages (TAMs) (IL-10, CCL2, CD68), M2 macrophages (CD163, VSIG4, and MS4A4A) and Tregs (FOXP3, CCR8, TGFβ)." (PMID 35096572, 2021). "CD68+/CD163+ TAMs were found to surround IR/IGF1R-stained PDAC tumor cells." (PMID 34638472, 2021). "Although CD68 has found use in clinical settings as the biomarker for macrophages for decades, the true function of CD68 in tumor immune regulation remains unclear." (PMID 34079767, 2021).